INS (insulin)
Diseases named in the same sentence as INS in open-access papers (continued):
Sharing a sentence is not in itself a finding about the gene and the disease.
type 2 diabetes (continued). "Metformin is an oral hypo-glycemic drug primarily used in the treatment of type 2 diabetes for its beneficial effects in reducing hepatic glucose synthesis and increasing peripheral tissue sensitivity to insulin, mainly through the stimulation of AMPK enzymes (AMP-dependent kinase)." (PMID 39518420, 2024). "The significantly higher efficacy of once-weekly insulin icodec compared to once- daily Insulin Glargine U-100 that it may be a preferred option for achieving excellent glycemic control in patients with type 2 diabetes." (PMID 38566252, 2024). "The BEYOND trial evaluated the feasibility of switching individuals with type 2 diabetes and inadequate glycemic control from a basal-bolus insulin regimen to a fixed-ratio combination (FRC) of basal insulin with a GLP-1 RA or a sodium-glucose co-transporter 2 inhibitor (gliflo-combo)." (PMID 37787888, 2024). "IR is physiologically defined as the inability of target tissues to respond to the action of insulin and is the pathogenic trigger for type 2 diabetes, non-alcoholic fatty liver disease, and atherosclerosis." (PMID 38786759, 2024). "Exercise is recommended in the treatment of type 2 diabetes and can improve insulin sensitivity." (PMID 38522033, 2024). "Currently, several myokines are described as involved in exercise adaptation, and some of them are proposed to facilitate the anti-inflammatory effects of exercise and, therefore, critically counteract insulin resistance and the metabolic dysfunction observed in obesity and type 2 diabetes." (PMID 38981607, 2024). "Moreover, dietary AGEs restriction has been shown to improve insulin sensitivity in patients with type 2 diabetes." (PMID 39201577, 2024). "Type 2 diabetes also called non-insulin-dependent diabetes or adult-onset diabetes includes people who are insulin resistant or insulin-deficient." (PMID 39011434, 2024). "The markedly elevated fasting plasma insulin levels of HFD-fed middle-aged mice compared to NCD-fed middle-aged mice may serve as indicative evidence of type 2 diabetes." (PMID 38255206, 2024). "Additionally, UCPs influence insulin sensitivity and lipid metabolism, linking them to obesity-related conditions like type 2 diabetes and metabolic syndrome." (PMID 39125390, 2024). "Consequently, blocking the degradation of insulin has emerged as a strategy for the management of type II diabetes." (PMID 38254517, 2024). "Therefore, we performed a subgroup analysis according to the different types of participants including type 1 diabetes, insulin-naïve type 2 diabetes, and previously insulin-treated type 2 diabetes." (PMID 39629047, 2024). "The rationale for this choice is that the oral hypoglycemic drug metformin is efficacious for the treatment of obesity consequent to type 2 diabetes, and that the principal targets of metformin include the liver (insulin functional agonism) and the brain (reduction of NPY orexigenic signals)." (PMID 38191558, 2024). "Drp1 also contributes to type 2 diabetes by affecting insulin secretion and function." (PMID 39763653, 2024). "This suggests that factors other than disease duration and insulin therapy may contribute to the development of pancreatic exocrine insufficiency in individuals with type 2 diabetes." (PMID 38398492, 2024). "Furthermore, in type 1 and type 2 diabetes, attention during pregnancy is focused on titrating insulin dosing using pens, continuous infusion sets (e.g., pumps) and continuous glucose monitors, while avoiding hypoglycemia." (PMID 38163872, 2024). "Initiation of insulin-based therapy among individuals with type 2 diabetes may be an indication of poorer glycemic control." (PMID 39020360, 2024). "This receptor also exerts an inhibitory influence on insulin secretion and previous studies have linked the lead SNP (rs10830963) located in the intron of the MTNR1B gene to FPG levels, HbA1c measurements, type 2 diabetes and birth weight." (PMID 38372780, 2024).
type 2 diabetes (continued). "Hypoglycemia may occur as a result of insulin overdosage in the treatment of type I diabetes, or as a result of sulphonylurea derivative use in the treatment of type II diabetes." (PMID 39062768, 2024). "Notably, the sample size of 60 patients divided into two groups is relatively small, potentially limiting the generalizability of findings to a broader population of inpatients with type 2 diabetes on intensive insulin therapy." (PMID 38476508, 2024). "The damage initiated to pancreatic beta cells through the development of type 2 diabetes is irreversible, and unfortunately lays the groundwork for the development of other factors of MetS likely through the effects of insulin." (PMID 38337589, 2024). "The once‐weekly insulin icodec, a new basal insulin analog, may positively support a reduction in injection frequency and improve adherence to therapy in type 2 diabetes (T2D) patients." (PMID 38659132, 2024). "In addition, by improving social jetlag we expect to improve glycemic and metabolic control, through improved insulin sensitivity and reduced HbA1c levels in people with prediabetes and type 2 diabetes." (PMID 38997765, 2024). "The ranking probability results suggested that once-weekly insulin icodec may be the preferred treatment option for patients with type 2 diabetes." (PMID 38172995, 2024). "Type 2 diabetes (T2D) is a metabolic syndrome characterized by inadequate insulin secretion and the reduced sensitivity of target organs to insulin, resulting in various metabolic disturbances, including disruptions in fat, protein, water, electrolyte balance, and other metabolic processes." (PMID 39458293, 2024). "However, insulin-stimulated glycogen synthesis was enhanced by roxadustat in myotubes from donors with type 2 diabetes." (PMID 38814443, 2024). "In summary, S1P plays multiple roles in both type 1 and type 2 diabetes, significantly affecting immune modulation and beta-cell protection in type 1 diabetes, and more profoundly influencing insulin sensitivity, lipid metabolism, and inflammatory responses in type 2 diabetes." (PMID 39777222, 2024). "Insulin-resistant, dysfunctional adipose tissue disrupts this crucial glucose–lipid (FFA) energy transition, causing metabolic inflexibility, a hallmark of insulin-resistant states such as obesity, metabolically associated fatty liver disease (MAFLD), and type 2 diabetes." (PMID 39768947, 2024). "Furthermore, we introduced two modified versions of the model to address specific considerations: one disregarding the impact of type 2 diabetes by assuming a constant insulin concentration, and another reducing the activation rate of microglia." (PMID 38586183, 2024). "Oxidative stress-mediated inactivation of SENP1 may be a critical step in impaired insulin secretion in type 2 diabetes." (PMID 39431155, 2024). "A 68-year-old male with a past medical history of type 2 diabetes who had been on insulin lispro protamine suspension for 15 years, hypertension, dyslipidemia, obstructive sleep apnea, and prior smoking was admitted for elective CABG due to severe coronary artery disease." (PMID 39421103, 2024). "Furthermore, a trend toward increased retinal blood flow in response to insulin infusion has been shown, whereas in people with type 2 diabetes, insulin is reported to decrease retinal blood flow." (PMID 39661465, 2024). "The once‐weekly insulin icodec, a new basal insulin analog, may positively support a reduction in injection frequency and improve adherence to therapy in type 2 diabetes (T2D)." (PMID 38659132, 2024). "However, if patients with type 2 diabetes need to receive insulin analogues that are more expensive, these preparations are available with 50% or 100% reimbursement coverage depending on the patients’ HbA1c levels." (PMID 38658983, 2024).
type 2 diabetes (continued). "The findings suggest that GEG has the potential to alleviate type 2 diabetes-induced intestinal dysfunction, enhance insulin production, and boost beta cell number (as evidenced by the observed increase in insulin-producing beta cells detected through insulin-immunohistochemistry staining)." (PMID 39199328, 2024). "This might be due to the fact that healthy lifestyle behaviors (i.e., diet and exercise) are directly related to insulin sensitivity, a key factor in the development of type 2 diabetes." (PMID 39519532, 2024). "This randomized controlled trial evaluated the immediate effect of RYGB, SG, or PSMF diet alone on beta-cell function in 30 patients with obesity and insulin-treated type 2 diabetes using a euglycemic clamp and a hyperglycemic clamp first in absence and then in the presence of glucagon." (PMID 38589596, 2024). "Defective insulin secretion and reduced tissue sensitivity are key features of type-2 diabetes." (PMID 38999937, 2024). "However, based on other cohort studies in countries with similar populations to the Netherlands, we estimate the proportion of insulin-dependent type 2 diabetes to be 10–20% of all type 2 diabetes." (PMID 39685759, 2024). "Habitual snoring and stopped breathing are linked to more abnormal glucose metabolism and insulin resistance in snorer individuals compared to non-snorers, which can exacerbate the progression of type 2 diabetes." (PMID 39081790, 2024). "The ingestion of a mixed-macronutrient meal augments differing temporal profiles in insulin clearance among individuals without type 2 diabetes, which is associated with HOMA-IR and the secretion of glucagon." (PMID 39138690, 2024). "Epigenetics plays a crucial role in developing type 2 diabetes and insulin function." (PMID 38805166, 2024). "Moreover, chlorogenic acid is a potential agonist of PPAR-γ regulating glucose homeostasis and increasing insulin sensitivity of peripheral tissues thus preventing type II diabetes." (PMID 39468643, 2024). "Therefore, a prospective, randomized trial was performed in 30 patients with insulin-treated type 2 diabetes and a body mass index ≥ 35 kg/m2." (PMID 38589596, 2024). "The significantly higher efficacy of once-weekly insulin icodec compared to once-weekly insulin Fc suggests that it may be a preferred option for achieving excellent glycemic control in patients with type 2 diabetes." (PMID 38172995, 2024). "The most common is type 2 diabetes resulting from the body’s ineffective use of insulin." (PMID 38598507, 2024). "According to a few studies, C-peptide may also be helpful in understanding the variability of type 2 diabetes and may offer helpful recommendations for the safe beginning and adjustment of basal insulin." (PMID 38654804, 2024). "Therefore, our data demonstrate that the majority of the IDDM sample is likely composed of type 2 diabetic patients who have progressed to insulin-dependency." (PMID 38596146, 2024). "The increased demand for insulin secretion explains why steatosis, independent of obesity, increases type 2 diabetes risk." (PMID 38334817, 2024). "Roxadustat may also improve insulin action on glycogen synthesis in myotubes from donors with type 2 diabetes." (PMID 38814443, 2024). "Evidence around the use of connected insulin devices in type 2 diabetes is still in an early phase." (PMID 38951212, 2024). "However, further research is needed on the site of fucoidan and protamine during binding, and the mechanism of insulin-loaded nanoparticles to improve insulin secretion in type 2 diabetic mice." (PMID 39458652, 2024). "While STZ robustly increases blood glucose, the induced loss of insulin producing cells is phenotypically similar to Type I diabetes, and not Type II diabetes that is prevalent in aging or with obesity." (PMID 38596458, 2024).
type 2 diabetes (continued). "Therefore, the objective of this study is to conduct a systematic review and network meta-analysis to evaluate the effect of the two most advanced once-weekly insulin analogues, namely insulin icodec and insulin Fc, in patients with type 2 diabetes." (PMID 38172995, 2024). "Type 2 diabetes mellitus (T2DM) occurs when the pancreas does not produce enough insulin or the body does not use it effectively, which causes glucose intolerance." (PMID 39596424, 2024). "Finally, we show that reduction of islet IGFBP7 in type 2 diabetes results in improved insulin secretion." (PMID 39280605, 2024). "Background and Objectives: Degludec (Deg) and glargine U300 (Gla-300) are insulin analogs with longer and smoother pharmacodynamic action than glargine U100 (Gla-100), a long-acting insulin that has been widely used for many years in type 1 and type 2 diabetes." (PMID 38541176, 2024). "Conversely, hyperinsulinemia is often observed in the early stages of type 2 diabetes to compensate for the decreased metabolic effects of insulin, and indeed, this hyperinsulinemia may enhance certain insulin actions." (PMID 39513056, 2024). "A variable number of tandem repeats (VNTR) in the insulin gene (INS) control region may be involved in type 2 diabetes (T2D)." (PMID 37624484, 2024). "Our observation of reduced insulin levels in the older male mice combined with glucose intolerance could be an indication of the development of type 2 diabetes." (PMID 39203867, 2024). "In the STYLCONNECT study, people with type 2 diabetes showed a strong interest in using a device that could automate the collection of their insulin data and integrate data from glucose measurement devices." (PMID 38951212, 2024). "After discontinuation of insulin, there was, however, progressive decline in glycaemic control over time as might be expected in people with type 2 diabetes." (PMID 38240751, 2024). "Type 2 diabetes (T2D) is a metabolic disease of complex etiology characterized by chronic hyperglycemia with the abnormal metabolism of carbohydrates, fat, and protein due to defective insulin secretion and function within the human body." (PMID 39797185, 2024). "In metabolic diseases like obesity and type 2 diabetes, therapies aimed at enhancing lipid oxidation in mitochondria or reducing lipid accumulation in LDs could improve insulin sensitivity and glucose homeostasis." (PMID 38999988, 2024). "Therefore, a randomized controlled trial was performed in patients with insulin-treated type 2 diabetes to measure beta-cell function and insulin sensitivity before and immediately after Roux-en-Y gastric bypass (RYGB) or sleeve gastrectomy (SG)." (PMID 38589596, 2024). "Despite a century of development and refinement of insulin therapy, hypoglycaemia remains the most common complication, affecting virtually all people with type 1 diabetes and most of those with insulin-treated type 2 diabetes." (PMID 38376580, 2024). "This randomized clinical trial examines whether a voice-based conversational artificial intelligence (AI) application can help patients with type 2 diabetes titrate basal insulin at home to achieve rapid glycemic control." (PMID 38039007, 2023). "For example, improper sorting of proinsulin for processing to insulin results in type 2 diabetes." (PMID 38435713, 2023). "Body mass index (BMI) emerged as the only significant risk factor for DPAD, DPN, and DFU, independent of type 2 diabetes, fasting glucose, fasting insulin, and HbA1c." (PMID 37989345, 2023). "Elevation in free fatty acid levels, especially that of saturated fatty acids such as palmitic acid (PA), results in impairment of insulin production and secretion, and β-cell apoptosis, which in turn leads to lipotoxicity, serving as a key player in the pathophysiology of type 2 diabetes." (PMID 36596838, 2023).
type 2 diabetes (continued). "The gene expression analysis of LCM-pooled islets revealed a prominent alteration of ER stress-related genes and evidenced their correlation with in situ proinsulin–insulin immunofluorescence data and in vivo beta cell dysfunction occurring during progression to type 2 diabetes." (PMID 36280617, 2023). "The objective of this study was to investigate whether placebo effect induced by pharmacological conditioning with intranasal insulin can affect glucose, insulin, C-peptide, hunger, and memory in patients with diabetes type 2 and healthy controls." (PMID 37234022, 2023). "Besides the different etiology of type 1 and type 2 diabetes, pancreatic beta cells have reduced or impaired insulin secretion in both and have reduced capability to compensate for the insulin demand to maintain normoglycemia." (PMID 37822597, 2023). "Postprandial glycemic excursions, associated with high levels of insulin and lipemia, have been implicated in the etiology of non-communicable diseases such as type 2 diabetes (T2D)." (PMID 37892479, 2023). "However, in Asian patients with longstanding type 2 diabetes, a therapy with premixed insulin following continuous subcutaneous insulin infusion (CSII) therapy was related to a higher risk of hypoglycaemia in normal-weight men." (PMID 36897358, 2023). "People who used insulin for the first time after 2013 most likely had type 2 diabetes." (PMID 37874829, 2023). "Advances in nanotechnology, molecular and biomedical imaging tools, and drug delivery systems are offering new opportunities for early diagnosis and monitoring disease progression in patients with type 1 or type 2 diabetes combined with diminished insulin secretion." (PMID 36770385, 2023). "HBO-mediated improvement of insulin sensitivity likely results from decreased endoplasmic reticulum stress and increased mitochondrial capacity, possibly leading to low-dose reactive oxygen species-mediated mitohormesis in humans with type 2 diabetes." (PMID 36178534, 2023). "In the trial that evaluated the efficacy and safety of imeglimin as a combination therapy with insulin in Japanese type 2 diabetic patients, the incidence of adverse events, serious adverse events, and hypoglycemia was similar in the imeglimin and placebo groups." (PMID 37237539, 2023). "This may be related to insulin resistance of pancreatic alpha cells which has been demonstrated in type 2 diabetes." (PMID 36752854, 2023). "Insulin treatment is widely used not only for type 1 but also for type 2 diabetes patients." (PMID 37259150, 2023). "A strength of the trial was the enrolment of individuals with type 2 diabetes, the population which could potentially benefit the most from once-weekly basal insulin." (PMID 37308751, 2023). "The dietary composition affects glycemia and insulin sensitivity in patients with type 2 diabetes; however, a diet composed of only specific macronutrients may be less beneficial and difficult to tolerate for a long period." (PMID 36804863, 2023). "The post hoc analysis of the DUAL VII Japan study found that switching from low‐dose premixed insulin to IDegLira in patients with uncontrolled type 2 diabetes (n = 39, mean baseline HbA1c 8.26% [67 mmol/mol]) resulted in improved HbA1c and generated weight loss." (PMID 36461758, 2023). "Over time, the decrease in insulin sensitivity may result in the development of type II diabetes mellitus, which is considered four times more likely in obese cats, as compared to lean cats." (PMID 37565085, 2023). "Further bioinformatics analysis revealed that the m6A modification may mainly participate in the insulin signaling pathway and type II diabetes mellitus pathway, which were closely related to IR and secondary hyperinsulinemia." (PMID 37550765, 2023). "Type 2 diabetes is caused by a relative lack of insulin secretion in the body,leading to metabolic disorders in the body." (PMID 39076862, 2023).